IL2 (interleukin 2)
Diseases named in the same sentence as IL2 in open-access papers (continued):
Sharing a sentence is not in itself a finding about the gene and the disease.
experimental autoimmune encephalomyelitis (17 papers, 2009 to 2025). An autoimmune demyelinating disease of the central nervous system that is produced experimentally in animals by the injection of homogenized brain or spinal cord in Freund's adjuvant. "In experimental autoimmune encephalomyelitis, miR-146a reduced Th17 differentiation by targeting IL-6 and IL-2." (PMID 35370692, 2022). "In the experimental autoimmune encephalomyelitis model of multiple sclerosis, β2-AR–mediated signaling was able to reduce the T cell-mediated autoimmunity in experimental autoimmune encephalomyelitis by suppressing IL-2, IFN-gamma, and GM-CSF production." (PMID 33142779, 2020). "Here we show that genetic deletion of Hrd1 in mice inhibits T-cell proliferation, production of IL-2, and differentiation of Th1 and Th17 cells, and consequently protects mice from experimental autoimmune encephalomyelitis." (PMID 27417417, 2016). "IL-2/anti-IL-2 complexes have been shown to induce Treg expansion, protecting experimental models from airway inflammation, experimental autoimmune encephalomyelitis (EAE), and conferring long term tolerance to pancreatic allografts." (PMID 23185394, 2012). "For example, IL-2–directed immunotherapies have been successful in ameliorating disease in experimental autoimmune encephalomyelitis, an animal model of MS." (PMID 19116909, 2009). "Treatment with recombinant HSPB1 has shown translational potential, reducing the paralytic symptoms when injected intraperitoneally in the experimental autoimmune encephalomyelitis mouse model, alongside decreased levels of the inflammatory cytokines IL-2, IL-6, and IFNγ." (PMID 38507480, 2024). "We also found that dexamethasone could allow Treg expansion induced by IL-2, and the combination of IL-2 and dexamethasone synergistically increased the number of Tregs and inhibited the development of experimental autoimmune encephalomyelitis (EAE) in mice." (PMID 33907514, 2021). "Combined IL-2 and IL-4 reduces the severity of experimental autoimmune encephalomyelitis (EAE)." (PMID 33617447, 2021). "Preclinical studies have shown that the delivery of IL-2/anti-IL-2-antibody complexes stimulates Treg expansion and reduces disease in models of T1DM, experimental autoimmune encephalomyelitis (EAE), collagen-induced arthritis, and angiotensin II-induced aortic stiffening." (PMID 29805313, 2018). "However, these FPs did not antagonize free monomeric IL-2 and lacked therapeutic efficacy in experimental autoimmune encephalomyelitis (EAE)." (PMID 33072087, 2020). "Therefore, treatment with the combination of IL-2 and a calcineurin inhibitor can induce Treg expansion while inhibiting the expansion of inflammatory cytokine-producing CD4+ T cells, resulting in an additive effect in experimental autoimmune encephalomyelitis." (PMID 38665907, 2024).
injury (17 papers, 2010 to 2025). Damage inflicted on the body as the direct or indirect result of an external force, with or without disruption of structural continuity. "In a mouse model of traumatic brain injury, IL-2 complex treatment was shown to alleviate inflammation and reduce blood-brain barrier disruption." (PMID 40948499, 2025). "One study used profiling assays analyzing cytokine regulation at various time points that indicated interleukin (IL)-1β, IL-17, and IL-2 to be of importance in a bleomycin-induced lung injury model." (PMID 33396865, 2020). "In addition, IL-2 can synergistically promote vascular leakage with TNF-α in superantigen or pathogen-induced acute lung injury." (PMID 38967887, 2024). "However, our findings suggest that T-cells and the IL-2 pathway could be involved in the progression of HI brain injury in the first 24 h after insult." (PMID 37998394, 2023). "When patients with primary MHTN related kidney injury have decreased CD4+CD25+ cells, their lymphocytes would react significantly more strongly to antigens, leading to higher levels of cytokine (IL-2, IL-4, and IL-6) production." (PMID 27278520, 2016). "The present study showed that CLEE could protect rats against TAA-induced liver fibrosis and kidney injury probably by (i) reduction of MDA, (ii) enhancement of GSH and CoQ10; and (iii) inhibition of the increase of inflammatory markers, IL2, CPR, TNF-α, NO that evoke oxidative stress." (PMID 36235007, 2022).
leishmaniasis (17 papers, 2013 to 2025). Infectious disease that is transmitted through the bite of hematophagous female phlebotomine sand flies. "In this sense, IL-2 may contribute to susceptibility or resistance in leishmaniasis, promoting activation of Th1 response as well as TNF which explains the strong correlation between these cytokines." (PMID 36017367, 2022). "Seder and colleagues (2008) proposed a model for the development of the CD4+ Th1 response in leishmaniasis, which involved the expression of different combinations of three proinflammatory cytokines: IL-2, TNF-α, and IFN-γ." (PMID 38410517, 2024). "Patients with recurrent leishmaniasis presented a positive correlation between the levels of IL-2, IL-4 and TNF (p<0.001)." (PMID 36017367, 2022). "Resisting leishmaniasis is concerned with a Th1 prevailing reaction as well as interleukin-2 (IL-2) and IFN- γ generation by the particular T lymphocyte+CD4 population of the antigen, through mediating protective cellular immune responses." (PMID 31579449, 2019). "Moreover, in previous studies, IP-10, and IFN-γ levels proved useful in monitoring the cellular immune response following treatment for active disease and IFN-γ, TNF-α, IL-10 and IL-2 indicated exposure to leishmaniasis." (PMID 40142579, 2025). "Additionally, as observed in the linear discriminant analysis, the levels of RANTES, IP-10 and IL-2 were higher among patients with Lg-CL compared to the healthy individuals, which confirms the possible role of these cytokines in the immunopathogenesis of leishmaniasis." (PMID 36091007, 2022). "Secretion of IL-12, IL-2, IFN-γ and TNF-α as cytokines released after activation of T helper 1 protects human against leishmaniasis." (PMID 28979355, 2017). "The degree of protection against various infections including leishmaniasis is predicted by the frequency of polyfunctional CD4+ memory T cells that produce IFN-γ, TNF-α, and IL-2." (PMID 26485398, 2015). "It clearly shows that an efficient vaccine against leishmaniasis should not only induce IFN-γ-, TNF- and IL-2-secreting memory T cells, but also needs to prevent the development of antigen-specific IL-10-secreting T cells." (PMID 23825956, 2013). "The production of IFN-γ, TNF-α, granzyme B, IL-5 and IL-10 by SLA-stimulated PBMCs, and of IFN-γ, TNF-α and IL-2 by SLA-stimulated whole blood, could be used to indicate exposure to leishmaniasis, especially for patients subjected to induced immunosuppression." (PMID 26496365, 2015). "In addition, while the subjects cured of leishmaniasis exhibited monofunctional cells that individually expressed all the analyzed molecules, CD8+ T cells from patients with active CL preferentially expressed granzyme B or IL-2." (PMID 30510917, 2018).
liver cancer (17 papers, 2015 to 2025). An epithelial or non-epithelial malignant neoplasm that arises from the liver. "Tregs reduced IL-2 levels in the liver cancer microenvironment through competitive uptake; however, IL-2 enhanced NK cell function and decreased lung metastasis of liver cancer in mice." (PMID 40160817, 2025). "Here the authors show that TET2 upregulates tumor cGAS to activate STING in endothelial cells, inducing tumor vascular normalization and enhancing efficacy of anti-PD-L1 alone or combined with IL-2 in liver cancer preclinical models." (PMID 38177099, 2024). "Excitingly, in addition to the combined anti-tumor effect of VC and anti-PD-L1, VC treatment further boosted efficacy of anti-PD-L1 combination therapy with IL-2 in both subcutaneously implanted tumor models and orthotopic liver cancer models." (PMID 38177099, 2024). "The induction of proinflammatory cytokine and chemokines (interleukin-2) is detrimental among primary liver cancer patients who have undergone hepatectomy." (PMID 37113696, 2023). "Further, IL-2 augments the sorafenib-induced apoptosis in liver cancer by promoting mitochondrial fission and activating the JNK/TAZ pathway." (PMID 36249790, 2022). "The levels of Treg cells and IL-2, IL-10, and TGFβ in the blood of patients with liver cancer were detected by flow cytometry and ELISA, respectively." (PMID 33204731, 2020). "Compared with healthy people, Treg cells and IL-2, IL-10, and TGFβ contents in peripheral blood of liver cancer patients were increased." (PMID 33204731, 2020). "Since IL2RB and IL2RG are sufficient to form functional receptor for transmitting signals from IL-229, liver cancer cells could also respond to IL-2 secreted by T cells and led to STAT5A activation." (PMID 38177099, 2024). "In this study, the increased expression levels of miR-544 was shown to be inversely associated with the decreased expression of RUNX3 and NCR1 in NK cells separated from patients with liver cancer, while miR-544 was downregulated in IL-2 activated-NK cells in vitro." (PMID 29636640, 2018). "Importantly, we further reveal that VC treatment induces tumor vascular normalization and boosts efficacy of anti-PD-L1 therapy or anti-PD-L1 combination therapy with IL-2 in vivo, provides promising strategies to enhance the combinational immunotherapy for liver cancer." (PMID 38177099, 2024). "Together, these results indicate that IL-2-activated STAT5A recruits TET2 binding to the cGAS locus to promote cGAS demethylation and transcription, leading to cGAS upregulation in liver cancer." (PMID 38177099, 2024). "In line with a previous study, SRE over 100 μg/mL is cytotoxic to a liver cancer cell line; however, 50 μg/mL of SRE has a 40% cytotoxicity and extremely released IL-2 in splenocyte-tumor coculture systems." (PMID 34659228, 2021). "In conclusion, we developed and empirically verified a new and simple ex vivo-expansion protocol using IL-2, IL-12, IL-18, CD16, CD56 and NKp46 for preparing high ratio of NK cells in effector cells (MYJ1633) and demonstrated their cytotoxicity against liver cancer in vitro and in vivo." (PMID 31426763, 2019).
Miscarriage (17 papers, 2012 to 2025). A pregnancy that ends at a stage in which the fetus is incapable of surviving on its own, defined as the spontaneous loss of a fetus before the 22th week of pregnancy. "In cases of miscarriage, the expression of B7-2 was found to be highly upregulated at the fetomaternal interface and this was associated with high levels of Th1 cytokines (IL-2 and IFN-gamma) and low levels of Th2 cytokines (IL-4 and IL-10)." (PMID 25189405, 2014). "A cut-off point of 2.55% for DPNKT-like cell subset in the blood and cut-off values of 39.5 and 20.5 pg/ml for the levels of IFN-γ and IL-2, respectively could be used for the prediction of the risk of spontaneous abortion." (PMID 34849421, 2021). "This might play an important role in pregnancy as IL-2 has been implicated to be upregulated in pre-eclampsia and miscarriage and IL-7/IL-7R signaling pathway in fetal miscarriage, due to the upregulation in the ratio of Th17/Treg cells." (PMID 32733490, 2020). "This study addresses an important gap by examining the differences in IL-2, IL-27, and IL-17 levels between recurrent miscarriage and healthy pregnancy in detail." (PMID 40141672, 2025). "The serum of miscarriage patients has been shown to contain significantly higher levels of specific inflammatory cytokines (IL-2, IL-17A, IL-17F, TNF-α, and IFN-γ)." (PMID 39203483, 2024). "Interleukin-2 (IL-2) is a cytokine that regulates NK cell activity and is elevated in miscarriage, PE, and RUPP rats." (PMID 33407826, 2021). "In the present study, the levels of different subsets of NKT-like cells and IFN-γ, IL-2, IL-4, and IL-17 cytokines were characterized and evaluated as potential immunological parameters that could be used for the prediction of pregnancy loss in women who had unexplained recurrent miscarriage (URM)." (PMID 34849421, 2021). "In agreement with a previous study, the results showed increased IL-2 (p < 0.05) and decreased IL-10 level in the embryonic miscarriage group compared with control." (PMID 33299847, 2020). "Additionally, the changes in IL-2, IL-17, and IL-27 in recurrent miscarriages can contribute to our understanding of the roles of these cytokines in immune responses and inflammation processes." (PMID 40141672, 2025). "Furthermore, women who have embryonic miscarriages exhibit higher vaginal levels of interleukin 2 (IL-2) and lower levels of interleukin 10 (IL-10) than control subjects." (PMID 35265534, 2022). "In this study, we assessed the levels of different subsets of NKT-like cells and specific related Th1(IFN-γ, IL-2)/Th2 (IL-4) and Th17 (IL-17) cytokines, and their ability to predict recurrent miscarriage in women who have experienced URM, by comparing different case and control groups." (PMID 34849421, 2021). "IL-2/IFN-γ and IL-4/IL-10 are secreted by Th1 and Th2 lymphocytes, respectively; therefore, the results from the previous studies support a shift from Th1 to Th2 signaling events during implantation; and preventing this shift is associated with miscarriage." (PMID 24926365, 2014). "Compared with the control group, the IL-2, IL-17A, IL-17, TNF-α, and IFN-γ levels of serum were increased significantly in the miscarriage group." (PMID 34966824, 2021). "Here we report that IL-2, IL-17A, IL-17F, TNF-α, and IFN-γ are significantly increased in serum of miscarriage patients." (PMID 33731680, 2021). "Multiplex analysis revealed markedly increased serum levels of IL-2, IL-17A, IL-17F, tumor necrosis factor-α (TNF-α), and IFN-γ in miscarriage patients than those in the controls." (PMID 33731680, 2021). "The current study also found that serum levels of IL-2, IL-17A, IL-17F, TNF-α, and IFN-γ were markedly increased in miscarriage patients compared to the controls." (PMID 33731680, 2021).
Miscarriage (continued). "Our results showed that the level of IL2 was higher, whereas IL10 was lower in the embryonic miscarriage group than the control group, suggesting IL2 is dominant than IL10 that resulted in immune system depression in the embryonic miscarriage group." (PMID 33299847, 2020). "In the human placenta, IL-2 is not detected at implantation sites, and women whose pregnancies end in miscarriage have significantly higher serum and endometrial levels of IL-2." (PMID 38275932, 2024). "DPNKT-like cells, IL-2 and IFN-γ may therefore be used as biomarkers to predict miscarriage in women who have suffered spontaneous abortion." (PMID 34849421, 2021). "In a previous study, we observed elevated levels of cytotoxic granules and inflammatory cytokines, such as IL‐2 and IL‐12, as well as of perforin and granzyme B, at the implantation site rather than at the systemic level in a murine miscarriage model induced by α‐galactosylceramide (α‐GalCer)." (PMID 35444491, 2022).
cognitive decline (16 papers, 2013 to 2025). "Our study found that higher baseline plasma levels of IL-2 were associated with a lower cognitive decline, and that plasma levels of IL-2 had a satisfactory discriminatory ability to detect cognitive decline in the aMCI group." (PMID 34122046, 2021). "In the aMCI group, higher plasma levels of IL-2 were associated with a lower cognitive decline." (PMID 34122046, 2021). "Recent work showed that local expansion of Treg in the brain through interleukin-2 overexpression reverses molecular and cognitive signatures of ageing such as gliosis, inflammation, and cognitive decline." (PMID 38581053, 2024). "Transient depletion of Tregs accelerate cognitive decline, whereas amplification of Tregs including the use of low dose IL-2 improve cognitive outcomes in the same APP/PS1 mice used in this report." (PMID 38111016, 2023). "While not excluding potential efficacy at different doses or treatment regimes, these results suggest the IL2 treatment is less efficacious in amyloid‐driven cognitive decline than in age‐related cognitive decline." (PMID 36975362, 2023). "Delivery of interleukin 2 into the brain via a blood–brain barrier crossing AAV vector prevents cognitive decline in the aging mice." (PMID 36975362, 2023). "IL-2 had a high discriminatory capacity for identifying cognitive decline, with an area under curve (AUC) of 85.7% in the aMCI group, and the AUC was slightly increased when combining IL-2 with Aβ or tau biomarkers." (PMID 34122046, 2021). "Plasma IL-2 levels had a satisfactory discriminating ability to detect cognitive decline in the aMCI group, and the discriminating potential was slightly increased when combined with Aβ and tau biomarkers." (PMID 34122046, 2021). "In terms of cytokine levels, IL-2 had a satisfactory discriminatory capacity for detecting cognitive decline in the aMCI group (AUC = 85.7%, 95% CI = 69.7–100%)." (PMID 34122046, 2021). "Consistent with our observation, showed that using the 4–6-week-old AD mouse model (APP/PS1), the amplification of Tregs by peripheral chronic low-dose IL-2 administration restored cognitive functions, whereas the transient depletion of Tregs accelerated the onset of cognitive decline." (PMID 38352237, 2024). "Higher CSF IL-2 levels have been associated with slower cognitive decline in patients with MCI, leading to suggestions that IL-2 might be explored as a potential treatment for AD44." (PMID 35079029, 2022). "In our study, patients with aMCI who had higher plasma levels of IL-2 may have more neuroprotective effects than those with lower plasma levels of IL-2, and these patients may thus have lesser cognitive decline." (PMID 34122046, 2021). "Higher baseline levels of IL-2, sCD40L, IL-8, and VEGF were associated with a lower annual cognitive decline in the aMCI group, and higher baseline levels of Aβ1–40, IFNγ, IL-5, IL-17A, IL-25, and FGF were associated with a rapid annual cognitive decline in the AD group." (PMID 34122046, 2021). "IL-2 may have a better discriminatory capacity for identifying cognitive decline than Aβ and tau biomarkers in patients with aMCI." (PMID 34122046, 2021). "Furthermore, IL-2, IL-17, IL-23, TNF-β, GM-CSF, MCP-1, RANTES, eotaxin, IL-4, IL-5, IL-10 and G-CSF are also closely related with cognitive decline with ageing, synaptic or neuronal loss, osteoarthritis cancer, lung senescence." (PMID 27105505, 2016). "In the aMCI group, higher baseline plasma levels of IL-2, sCD40L, and VEGF were associated with a lower cognitive decline, and in the AD group, higher baseline plasma levels of IFNγ, IL-5, IL-17A, IL-25, FGF, GM-CSF, and VEGF were associated with a more rapid cognitive decline." (PMID 34122046, 2021). "Briefly, our study suggests that initial plasma levels of several cytokines were associated with subsequent annual MMSE changes in patients with aMCI or AD, and that plasma levels of IL-2 may be a potential biomarker to detect rapid cognitive decline in the aMCI group." (PMID 34122046, 2021).